EGF (epidermal growth factor)
Diseases named in the same sentence as EGF in open-access papers (continued):
Sharing a sentence is not in itself a finding about the gene and the disease.
cancer (continued). "Epidermal growth factor (EGF), an upstream effector of PTTG, induces PTTG expression by a paracrine mechanism, leading to activation of the EGF receptor (EGFR) and promoted cancer cell proliferation." (PMID 26516926, 2015). "Conversely, TAMs secrete epidermal growth factor (EGF) and activate the EGF receptor (EGFR) on the cancer cells." (PMID 26243145, 2015). "G-MDSCs induce EMT in cancer cells using TGF-β, epidermal growth factor (EGF), and hepatocyte growth factor (HGF)." (PMID 26078490, 2015). "EGF-mediated PTX3 secretion resulted in the enhancement of cell migration and invasion, and interactions between cancer and endothelial cells." (PMID 25797258, 2015). "Epidermal growth factor (EGF) has been shown to be a potent EMT inducer in a variety of solid tumors, including cervical, ovarian, and endometrial cancer." (PMID 26356073, 2015). "Up-regulated genes due to the down-regulation of microRNAs by EGF, bFGF, and IGF-1 treatment were predicted to target EGFR, FGFR, and IGFR, respectively, via cytokine-cytokine receptor interaction in the cancer pathway." (PMID 25938966, 2015). "On the basis of this, it is reasonable to assume that blocking EGF signaling will affect CSN6-E6AP axis to stop the viral life cycle and cancer transformation." (PMID 26318036, 2015). "Taken together, these results are consistent with a new paradigm for the role of EGF and BMPs in controlling MMP gene expression in cancer cells." (PMID 25897433, 2015). "In this study, to determine the importance of HA/CD44 in TGF-β1-induced EGF signaling activation and EMT in cancer cells, we used the HAS inhibitor, 4-MU, to block HAS expression and shRNA targeting CD44 to knockdown CD44 expression." (PMID 26005723, 2015). "The GG cell lines were cultured as neurospheres in serum free media supplemented with EGF and FGF, favoring the growth of undifferentiated, cancer stem-like cells." (PMID 25894595, 2015). "Cripto, the founding member of the EGF-CFC genes, plays an essential role in embryo development and is involved in cancer progression." (PMID 25629528, 2015). "In cancer EMT, signals emanate via factors, including transforming growth factor-β, hepatocyte growth factor, epidermal growth factor and hypoxia." (PMID 25586771, 2015). "For example, the 11 members of the epidermal growth factor (EGF) family act as both mitogens and motogens of epithelial cells, the precursors of carcinomas." (PMID 26287249, 2015). "Certain previous studies have shown that EGF stimulates the expression of MMP1 and MMP9 in several cancers." (PMID 24765152, 2014). "Our and other laboratories have reported that a specific inhibitor for EGFR efficiently blocked EGF-induced activation of MMP9 and reduced cancer invasiveness." (PMID 25380967, 2014). "Epidermal growth factor (EGF) is present at high concentrations in human saliva and modulates the growth and differentiation of various cancer cells." (PMID 24765152, 2014). "Cripto (also called Teratocarcinoma-derived growth factor), the original member of the vertebrate EGF-CFC family, plays a key role in all of these pathways and is deeply involved in early embryo development and cancer progression." (PMID 24805056, 2014). "EGF and IGF are critical regulators of the biological characteristics of cells, especially in cancers." (PMID 24618737, 2014). "SKOV-3 cancer cells were pretreated with 20 μM of U73122 for 1 hour, followed by PAF or EGF stimulation for 5 min." (PMID 25261977, 2014). "were shown to inhibit epidermal growth factor (EGF)-induced malignant transformation of mouse epidermal JB6 P+Cl41 cells, to possess potent antioxidant properties, and to induce apoptosis in human cancer cells." (PMID 24473167, 2014). "In these starvation experiments, designed to increase the population of cancer stem-like cells, we were able to enrich the proportion of CD44-positive cells by culturing in low serum containing cell medium with EGF and bFGF." (PMID 24122205, 2014).
cancer (continued). "Therapeutic targeting of EGF/EGFR and VEGF/VEGFR signaling is a major approach of anti-cancer therapy." (PMID 24945674, 2014). "Epidermal growth factor (EGF) and insulin-like growth factor-I (IGF-I) are critical regulators of cell differentiation, survival, proliferation, and migration in cancers." (PMID 24618737, 2014). "Epidermal growth factor inhibitors (EGFRI), the first targeted cancer therapy, are currently an essential treatment for many advance-stage epithelial cancers." (PMID 24723942, 2014). "Since EMT is generally associated with a migratory phenotype that is indispensable for cancer metastasis, we performed wound-healing assays in MCF-7 cells treated with TGFβ1 or TGFβ1/EGF." (PMID 25277187, 2014). "It has been reported that EGFR inhibition efficiently blocked EGF-induced activation of MMP9 and cancer invasiveness." (PMID 25380967, 2014). "By using serum-free medium containing the growth factors bFGF and EGF for cell culture, we were able to enrich and harvest CSC-like UM1 cancer cells." (PMID 24423398, 2013). "In cancer cells, ERK5 is required for EGF stimulation of cell proliferation; inhibition of ERK5 reduces the number of proliferating cells." (PMID 23630619, 2013). "In cancer cells, the extracellular domain of the EGFR binds to the EGF and the EGF pathway is activated; signaling is initiated to regulate the differentiation, survival, proliferation and migration of cancer cells." (PMID 23420529, 2013). "In cancer cells, ZIP7 induces the release of zinc into the cytosol and the resulting increased intracellular zinc level regulates the epidermal growth factor (EGF)/insulin-like growth factor (IGF) signaling pathway." (PMID 23505453, 2013). "In many cancers, EGFR evades degradation by entering the recycling pathway, and this invites a role for PKC and the pericentrion in these EGF-induced oncogenic properties." (PMID 24244711, 2013). "Most of cancer tissues are shown to overexpress EGFR, and EGF-EGFR axis has been considered a attractive target for cancer treatment." (PMID 23592411, 2013). "It is widely accepted that EGF, vascular endothelial growth factor, bFGF and EGFR are correlated with cancer cell growth." (PMID 23946783, 2013). "As one of the crucial cancer pathways, the RTK/ERK pathway is said to be one of the important links in cancer's development, containing a number of genes (EGFR, EGF, CCND1, MAPK3, etc.)." (PMID 24223781, 2013). "EGF family members, such as EGF and TGF-α, stimulate not only cell growth but also cell migration in cancer cells." (PMID 23917679, 2013). "Thus, AR/Src complex regulates multiple processes in EGF-stimulated HT1080 cells and led us to conclude that prevention of AR/Src Association, independent of the presence of androgens, impairs several properties that are crucial for cancer progression and invasiveness." (PMID 24130806, 2013). "Since the cells were cultured in serum-free medium containing bFGF and EGF, very likely these growth factors up-regulated the expression of kinases such as MSK-1 in a small subset of UM1 cancer cells (CSC-like cancer cells) and subsequently activated CREB-1." (PMID 24423398, 2013). "However, it remains to be elucidated whether EGF is secreted by cancer or stroma cells." (PMID 23056514, 2012). "The first candidate is EGF, which is known to be able to induce EMT phenotype in several cancer cell lines including HNSCC." (PMID 22315058, 2012). "Cancer patients are reported to have elevated serum levels of growth factors, namely hepatocyte growth factor (HGF), epidermal growth factor (EGF), transforming growth factor-beta (TGF-β) and insulin-like growth factor-1 (IGF-1), among others." (PMID 22432005, 2012). "The stimulation by many growth factors, including IGF-1, PDGF, EGF, and TGF-β, has been shown to induce the expression of VEGF-C in malignant tumors." (PMID 22496919, 2012).
cancer (continued). "Among the new strategies in the efforts of treating malignant tumours expressing different growth factors, and more specifically IGF-I, TGF beta, VEGF, or EGF, the anti-gene therapy approach, either antisense or triple helix, appears as a promising solution." (PMID 22400112, 2012). "Because Arf6 has been identified to play an important role in cancer cell migration and the PH domain of GEP100 links EGFR signaling to Arf6 activation, it is worthwhile to explore whether the PH domain of GEP100 is involved in EGF-induced Arf6 signaling pathway and cancer cell migration ability." (PMID 22701712, 2012). "The deregulation of many signaling pathways such as EGF/RAS/RAF/MEK/ERK and PI3K/AKT/mTOR is considered to play a critical role in oncogenesis and cancer progression." (PMID 24281308, 2012). "In vitro assay using purified MDSC showed that TGF-β, EGF, and HGF signaling pathways are all used by MDSC to induce EMT in cancer cells." (PMID 21980263, 2011). "VEGF, PDGF, EGF, FGF, and IGF, growth factors that facilitate high vascularity and cancer cell proliferation, are expressed not only in cancer cells but also in other surrounding cells." (PMID 22187659, 2011). "While EGF first stimulates the activation of the EGFR and subsequently increases cancer cell proliferation, EGF concurrently induces the activation of ROCK, which then turns off the activated EGFR pathway via a negative feedback system." (PMID 21722395, 2011). "The first injection of EGF-SEA solution was performed 2 days after inoculation of mice with S180 cells and the EGF-SEA protein reached the colonial S180 carcinomas 18 hrs later." (PMID 21311755, 2011). "The epidermal growth factor (EGF) family of proteins, and in particular HER2, promote androgen independent cancer growth, as can fibroblast growth factors and insulin-like growth factor-1 (IGF-1)." (PMID 20406442, 2010). "Previous reports including our own have shown that an overexpression of this receptor is associated with a high invasive and metastatic capacity of NSCLC, and also EGF-induced, NSCLC cells, among other cancer types." (PMID 20736951, 2010). "In solid tumours, new drugs targeting EGF- or VEGF- receptors are now approved and are entering clinical practise for treatment of colon, lung, kidney and other cancers, either alone or in combination with conventional treatment approaches." (PMID 20398256, 2010). "Epidermal growth factor (EGF) and its receptor (EGFR) as well as the EGFR-coupled Ras > Raf > MEK > ERK pathway are known to affect the survival of cancer cells upon therapeutic treatment." (PMID 20428086, 2010). "Angiogenesis, which is critical for cancer progression, is controlled by a variety of factors known to stimulate blood vessel growth and/or maturation, including VEGF, TGF-β, EGF, bFGF and TNF-α." (PMID 19696929, 2009). "Epidermal growth factor/EGFR autocrine and paracrine processes driving tumour cell proliferation has formed the basis for chemotherapeutic drug targeting of EGFR in some cancers." (PMID 19088723, 2009). "Cancer cells expressing MS4A12, in contrast, are sensitized to EGF and respond to low concentrations of this growth factor." (PMID 19781065, 2009). "As mTOR signalling is dependent on growth factors, including EGF, we compared everolimus with gefitinib or cetuximab in both wild type and EGFR inhibitor-resistant cancer cell lines, focusing on the mTOR effector p70S6 Kinase." (PMID 18319715, 2008). "EGF and IGF are potent survival factors, and their receptors are often constitutively activated in cancer cells leading to increased proliferation and resistance to apoptosis." (PMID 19784388, 2008). "In this regard, VEGF isoforms and their tyrosinekinase receptors VEGFRs, as well as epidermal growth factor (EGF) and itsreceptor (EGFR) are currently explored in clinical trials as drug candidatesagainst cancer." (PMID 18464916, 2008).
cancer (continued). "In fact, epidermal growth factor (EGF) and its receptor EGFR has been well documented to couple with Src kinase to regulate cancer progression." (PMID 18711637, 2008). "It’s role in EGF and IGF-1 signaling and increased secretion in cancer however, indicate that it plays a significant role in endometrial carcinogenesis and therefore is a rationale target for development of drugs and biomarker panels." (PMID 19784388, 2008). "As a functional consequence of multiple signaling pathway inhibition and interference with transcriptional regulation, ENMD-1198 significantly inhibited both EGF- and HGF-mediated cancer cell migration and invasiveness." (PMID 18651980, 2008). "Increased expression of the epidermal growth factor (EGF) receptors, HER1 and HER2 are related to poor prognosis in most cancers studied." (PMID 16685269, 2006). "The expression of mRNA for aFGF (3.7-fold), bFGF (2.6-fold), PDGF C (2.8-fold) and CTGF (2.2-fold) was also higher in cancer tissue, while that for PDGF A (−1.1-fold) and EGF (−2.5-fold) was lower." (PMID 15365564, 2004). "In fact, it has been shown that EGF and TGF-α can upregulate the production of VEGF, currently regarded as the major proangiogenic factor for most types of human cancer." (PMID 12618892, 2003). "Furthermore, it interacts with Wnt/β-catenin signalling and with epidermal growth factor (EGF) signalling to enhance epithelial-mesenchymal transition (EMT) and maintenance of cancer stem cells (CSC)." (PMID 41476776, 2026). "Human lung fibroblasts, especially when activated into CAFs, secrete cytokines and growth factors (like TGF‐β, IL‐6, PDGF, EGF, HGF, CXCL‐12), ECM proteins, and remodeling enzymes like MMPs and pro‐invasive signals that potentiate cancer stemness and metastasis." (PMID 41537745, 2026). "NFκB is activated by the EGF/EGFR pathway, contributing to inflammation and cancer progression." (PMID 40292295, 2025). "Moreover, several regulator proteins, growth factors, and cytokines, like IFN-γ, EGF, and TNF, exert their oncogenic effect by upregulating MMP-9,30, 31, 32, 33 suggesting its central role in cancer progression." (PMID 41273852, 2025). "Another study developed a multi-epitope vaccine targeting important cancer antigens like STAT3, HER2, and GRB7 using a multimodal strategy that included MHC I, MHC II, CTL, and B-cell epitopes created from MAGE-A3, EGF, and MUC-1 by in silico immunoinformatics techniques." (PMID 40453095, 2025). "“Pathways in cancer” pathway, represented by genes ITGB1, STAT5A, and EGF." (PMID 40621499, 2025). "Additionally, 8 upstream regulatory proteins were predicted to be activated, including Rab-like protein 6 (RABL6), heat shock factor 1 (HSF1), epidermal growth factor (EGF), and ERBB2, all of which are involved in the progression of various cancers." (PMID 40301999, 2025). "Interestingly, EGF-activated Akt induces the phosphorylation of Acapin at its Ser247 residue (AcapinS247), which promotes ARF6 GTPase activity for powering cancer cell migration." (PMID 40082743, 2025). "Oncogenic alterations in ERBB family members, including epidermal growth factor (EGF) and epidermal growth factor receptor 2 (EGFR2), promote cancer cell evasion of immune surveillance, thereby indirectly leading to an increase in the number of inflammatory cells in the TME." (PMID 40165901, 2025). "TRPM7 was overexpressed in NSCLC cell line A549 after stimulation with epidermal growth factor (EGF), with consequent increase in cell migration: both TRPM7-KO and the use of Waixenicin A counteracted the elevation in TRPM7 levels and had anti-cancer stem cell (CSC) effects." (PMID 39940997, 2025). "Additionally, miR-221 and miR-222 are modulated by EGF and mesenchymal-epithelial transition (MET) proto-oncogene receptors in tyrosine kinase inhibitor-resistant NSCLC, further contributing to cancer progression." (PMID 40430112, 2025). "The pathway enriched in “Pathways in Cancer” with 15 genes, including ITGB1, STAT5A, and EGF." (PMID 40621499, 2025).
cancer (continued). "Cancer’s disrupted criticality cascade parallels recent findings, where EGF stimulation failed to activate the Maxwell’s demon-like function of CP genes." (PMID 40943346, 2025). "We compared the strength of TGF/EGF communications to fibroblasts from cancer cells compared to those sent to fibroblasts by non-cancer cells, using linear models." (PMID 40341770, 2025). "Moreover, various pro‐inflammatory markers i.e., IL‐1, IL‐6, TNF‐α, IFN‐γ, TGF‐β and growth factors (VEGF, EGF, IGF‐2) are also involved in cancer progression." (PMID 40755497, 2025). "Genes like EGF and SRC contribute to this metabolic shift by activating PI3K/AKT and MAPK signaling pathways, which enhance glucose uptake, lipid biosynthesis and amino acid metabolism-key hallmarks of cancer metabolism." (PMID 40226632, 2025). "This could be achieved through co-administration of EGF or by conjugating EGF to PAMAM dendrimers, as has been reported for targeting cancer cell surfaces." (PMID 39319862, 2025). "Finally, we showed that osimertinib, an anti-cancer drug/EGFR inhibitor, blocked EGF-stimulated OAT3 transport activity." (PMID 40733034, 2025). "Despite the lack of clarity on the precise mechanism by which NaV1.7 contributes to cancer progression and metastasis; many studies have suggested a connection between NaV1.7 and proteins involved in multiple signaling pathways such as PKA and EGF/EGFR-ERK1/2." (PMID 39045054, 2024). "Integrins induce EGFR activation in the absence of EGF in normal epithelial cells and in cancer cells." (PMID 39594667, 2024). "The scRNA-seq data from four different cancer cell lines (A549, DU145, MCF7, and OVCA420) revealed that signaling pathways known to drive EMT- like TGFβ1, EGF, and TNF- converge on NF-κB and FOSL1, before initiating the expression of typical EMT master regulators such as STAIL, TWIST, and ZEB." (PMID 38856747, 2024). "EGF/EGFR signaling between TAMs and cancer cells was essential for spheroid formation." (PMID 39513610, 2024). "Following the analysis, 16 genes were then subjected to the network and pathway analyses, which revealed that these genes are involved in several cancer-related pathways including Jak-stat signaling, MAPK cascade, epidermal growth factor signaling, TNF signaling pathways, and many others." (PMID 38172584, 2024). "In particular, EGF and another ERBB ligand, Heregulin1 (HRG1), could protect cancer cells from action of lapatinib." (PMID 39403185, 2024). "Other growth factors such as Epidermal growth factor (EGF) and fibroblast growth factor (FGF) have been tied to cancer cell proliferation, differentiation and survival in the case of EGF, while FGF additionally acts as a pro-angiogenic factor by synergistically acting with VEGF." (PMID 38254117, 2024). "Indeed, we observed significant enrichment of physiological and cancer-related functions, which include but are not limited to gland formation, tube and vasculature morphogenesis, cell proliferation, and TGF-b or EGF signaling." (PMID 39766916, 2024). "Moreover, EGF secreted by TAMs increases the expression of αMβ2 integrin in TAMs and ICAM-1 in cancer cells to facilitate adhesion between TAMs and cancer cells." (PMID 39513610, 2024). "Additionally, EGF-induced GRB7 tyrosine phosphorylation activates Ras-GTPases and extracellular signal-regulated kinases 1/2 (ERK1/2) contributes to cancer proliferation." (PMID 39204147, 2024). "We specifically presented the analysis results for the EGF signaling pathway, where high PAK2-expressing cancer cells might play a crucial role as key signal transduction nodes, particularly as signal receivers." (PMID 38343537, 2024).